IL32 (interleukin 32)
Diseases named in the same sentence as IL32 in open-access papers (continued):
Sharing a sentence is not in itself a finding about the gene and the disease.
cancer (continued). "IC50 experiments also demonstrated that the use of an IL32‐neutralizing antibody reversed the repressive effect of CM from PCs on cancer cell sensitivity to third‐generation TKI drugs." (PMID 39435643, 2024). "We firstly checked the genetic alterations of IL32 genes in cancer patients using cBioPortal database." (PMID 38584169, 2024). "Functional assays highlight PCs' role in regulating cancer cell sensitivity to TKIs, mitigated by depleting IL32 or blocking its receptor β5‐integrin." (PMID 39435643, 2024). "Our research results indicate that IL32 is significantly overexpressed in 25 out of 33 cancer types, with a decrease in expression observed only in THCA and KICH." (PMID 38584169, 2024). "In summary, our findings indicate that pericyte‐derived IL32 activates the β5‐integrin mediated Src‐Akt signaling pathway, thereby negating the inhibitory effects of TKIs on this pathway in EGFR‐mutated cancer cells." (PMID 39435643, 2024). "IL-32 is an inflammatory cytokine that plays a role in the human immune system and has garnered extensive attention in cancer research in recent years." (PMID 38584169, 2024). "IL32 then activates the β5‐integrin‐Src‐Akt pathway, which impairs TKI effectiveness in EGFR‐mutated cancer cells." (PMID 39435643, 2024). "This research aimed to investigate the correlation between IL32 expression and immunity and visualize its prognostic landscape in pan-cancer." (PMID 38584169, 2024). "The UniCox and Kaplan–Meier survival analyses were utilized for exploring IL32 prognostic value in pan-cancer." (PMID 38584169, 2024). "It is found that YY1 transcriptionally upregulates IL‐32 secretion in pericytes, which binds to and activates β5‐integrin in cancer cells, triggering the Src‐Akt signaling pathway and reducing TKI sensitivity." (PMID 39435643, 2024). "IL-32 is a pleiotropic cytokine with classical pro-inflammatory functions as well as more unconventional roles in cancer, autoimmune diseases, and infections." (PMID 36875074, 2023). "Interleukin (IL)-32 is involved in the progression of several cancer types and a range of inflammatory diseases." (PMID 37313466, 2023). "In the same study, IL-32 protein stability was shown to be regulated by ADO in the RKO cancer colon cell line." (PMID 37313466, 2023). "IL-32θ, one of the IL-32 isoforms, has been shown to modulate cancer development and inflammatory responses." (PMID 37228610, 2023). "IL-32 mRNA expression is a prognostic factor in MM and is upregulated in cancer cells of patients that have relapsed from treatment." (PMID 37313466, 2023). "For example, in bladder cancer, TIGIT + Tregs accumulated around cancer tissues, promoted cancer cell metastasis and suppressed the antitumor immune response by promoting IL-32 expression in Tregs." (PMID 37670328, 2023). "Aberrant expression of IL-32 has been detected in numerous types of cancer, but it was poorly understood how EV-IL-32 derived from ESCC cells participated in the metastasis of ESCC." (PMID 35428295, 2022). "IL-32 is a pro-inflammatory cytokine involved in cancer-related inflammation and is upregulated in several malignancies." (PMID 35739379, 2022). "Hexanoic acid also exerted a potential positive role as immune system modulator in the regulation of Interleukin-32, an important cytokine involved in inflammation and cancer development." (PMID 35745219, 2022). "IL-32 is a pluripotent pro-inflammatory cytokine involved in a range of diseases including cancer, infections, and autoimmunity." (PMID 35005550, 2022). "IL32, identified as constitutive MAEs in BMMCs, T cells, and NK cells, is a cytokine involved in inflammation and cancer development." (PMID 34722498, 2021). "IL-32 enhances NK cell cytotoxicity and is used to improve the efficiency of NK cell-based immunotherapy against cancers." (PMID 34516566, 2021). "IL-32 also augmented the cytotoxic effect of NK-92 cells on the cancer cells through activation of DR3 and caspase-3 cell signaling." (PMID 34414188, 2021).
cancer (continued). "Although many studies have revealed the mechanism of the role of IL-32 isoforms in various types of cancers, the role of IL-32 is controversial and still unclear." (PMID 34682815, 2021). "Interleukin-32 (IL-32) is well known as a proinflammatory cytokine that is expressed in various immune cells and cancers." (PMID 34682815, 2021). "Recently, IL32 expression and cancer-related immune cells have been reported to be highly correlated in various types of cancers." (PMID 34682815, 2021). "Based on various databases, we investigated the correlation between IL32 expression levels and cancer patient outcomes." (PMID 34682815, 2021). "There is no data linking IL-32 with G-CSF but GM-CSF, a colony-stimulating factor with overlapping functions in cancer, have been shown to induce expression of various isoforms of IL-32 in eosinophils." (PMID 33020452, 2020). "As such, IL-32 represents a promising modulator of intratumoral DC and macrophage function and thus, a potentially novel molecular target for myeloid cell–based cancer immunotherapy." (PMID 32841222, 2020). "We show that IL-32 gene expression positively correlates with mature DC in all 33 examined cancer types from TCGA." (PMID 32841222, 2020). "As general cancer marker (all cancer patients analyzed against healthy controls), IL-32 was characterized by excellent accuracy and sensitivity but only fair specificity." (PMID 33020452, 2020). "We and others have repeatedly documented dissimilarities between left- and right-sided cancers, not only locally but also at systemic level and now we showed the contribution of IL-32." (PMID 33020452, 2020). "Several studies on the SNP of IL-32 in cancer have been reported in recent years, and IL-32 has even been linked to the patient outcome in some cancers." (PMID 33204366, 2020). "IL-32 expression was highest in T lymphocytes and significantly higher in NK and endothelial cells compared with cancer cells." (PMID 32841222, 2020). "Consistently, the involvement of IL-32 has been documented in infectious diseases, chronic inflammatory conditions, including gastritis and inflammatory bowel disease, and in cancer." (PMID 33020452, 2020). "Cancer patients, regardless location, had significantly elevated circulating IL-32 as compared to healthy controls." (PMID 33020452, 2020). "Difference between cancers regarding interleukin concentration was notable also locally, although positive correlation between systemic and local IL-32 was found only in GC patients." (PMID 33020452, 2020). "(B and C) IL32 transcript expression across multiple different cancer lines organized by cancer type from the NCI-60 Cancer Cell Line database and the Cancer Cell Line Encyclopedia, respectively." (PMID 30953519, 2019). "Recently, IL-32 has been shown to act as a potent inducer of cell migration in several types of cancer." (PMID 31201646, 2019). "Numerous studies have been published on the role of IL-32 in cancers and cancer- related malignancies." (PMID 29190960, 2017). "Together these data support the association of MYBL1, IL32, TMEM158 and ETS1 with certain TNBCs and the enrichment of genes involved in immune related processes as differentially associated with the cancers." (PMID 28966727, 2017). "Because TNBC are heterogeneous and immune-related genes appear to play a pivotal role in these cancers, we chose to examine the transcriptomes of the different cell lines based on IL32 expression." (PMID 28966727, 2017). "Because numerous studies have linked inflammatory cytokines to cancer progression, the effect of IL-32 has been investigated in various inflammatory disorders as well as several cancers." (PMID 27589563, 2016). "The exact mechanism involved in induction is overexpression of IL-32 which is still controversial but chromosomal region 16p13.3 was reported to be amplified and transcribed in cancer of small intestine and breast." (PMID 27143819, 2016).
cancer (continued). "Collectively, miRNA regulation of the expression of interleukins (IL-11, IL-1β, IL-24 and IL-32) emerges as a useful tool in probing modulatory mechanisms of cancer promotion/suppression and their (in)direct implication in immunotherapeutic approaches." (PMID 25590298, 2015). "Concurrently, miRNA regulation of the expression of interleukins (IL-11, IL-1β, IL-24 and IL-32) emerges as a useful tool in probing modulatory mechanisms of cancer promotion/suppression and their (in)direct implication in immunotherapeutic approaches." (PMID 25590298, 2015). "IL-32 plays various roles in cancer biology such as cancer cell survival as well as apoptotic death in accordance with each IL-32 isoforms." (PMID 26516703, 2015). "In our study, IL-32 expression in cancer cells was immunohistologically evaluated, and the clinical implications of IL-32 positivity with CRC metastasis were analyzed and discussed." (PMID 25889282, 2015). "Limited data exist describing the IL32 cytokine in cancers; however there is evidence the gene is suppressive in some cancers and facilitative in other cancers." (PMID 25100201, 2014). "The role of IL32 has also been examined in cancers, supporting the myriad of data supporting a relationship between inflammation and cancer." (PMID 25100201, 2014). "IL-32 is a proinflammatory cytokine involved in several diseases, including infections, chronic inflammation, and cancer." (PMID 25386048, 2014). "Numerous studies have highlighted the diverse roles of IL-32 in various cancers." (PMID 41181127, 2025). "However, realizing these potential applications requires more basic research and clinical trials to validate the roles and clinical value of IL-32 isoforms in different cancers." (PMID 38584169, 2024). "Depleting pericyte‐derived IL32 or blocking its putative receptor β5‐integrin could reverse their inhibitory effect on TKI sensitivity in cancer cells." (PMID 39435643, 2024). "Co‐culture and conditioned medium experiments demonstrate that PCs reduce TKI effectiveness in EGFR‐mutated cancer cells, a reversible phenomenon through silencing IL32 expression in PCs or depleting the IL32 receptor β5‐integrin on cancer cells, thereby restoring cancer cell sensitivity." (PMID 39435643, 2024). "CCL7, CCL23, and IL-32 attract monocytes and macrophages to regulate cancer antigen presentation." (PMID 39235457, 2024). "ENO1 and IL-32 commonly act on the development and progression of cancer." (PMID 38675491, 2024). "Indeed, several studies have demonstrated the presence of IL-32 in intracellular membrane vesicles of cancer cells and postulated the secretion of IL-32 through EVs." (PMID 39211051, 2024). "Therefore, we studied the correlation between IL32 expression and the level of immune infiltration in 33 types of cancer using the XCELL database." (PMID 38584169, 2024). "Additionally, we demonstrate that IL32 depletion or the use of integrin inhibitors can effectively counteract the inhibitory effect of PCs on cancer cell sensitivity to TKI in vivo." (PMID 39435643, 2024). "The roles of IL-32 isoforms in cancer suggest that they may become new therapeutic targets or biomarkers for cancer diagnosis and prognosis evaluation." (PMID 38584169, 2024). "To further clarify the role and specific mechanisms of IL32 in various cancers, we utilized GO enrichment analysis to predict the speculated biological functions and related signaling pathways of IL32 in pan-cancer." (PMID 38584169, 2024). "IL-32 has also been shown to promote proliferation and survival of the cancer cells." (PMID 36875074, 2023). "Increased levels of IL32 were found in cancer tissue, and primary CRC lymph nodes metastasis." (PMID 37228491, 2023). "IL-32 is a pro-inflammatory cytokine expressed by several types of cancer cells and immune cells." (PMID 37313466, 2023). "The function of IL-32 is not fully understood in cancer development." (PMID 38258051, 2023).
cancer (continued). "Notably, under these analysis settings, only 19 genes were differentially regulated in CCD8 cells in direct contact with cancer cells and only one gene (IL32) was differentially regulated in CCD8 in indirect contact with cancer cells." (PMID 36936987, 2023). "To further characterize how IL-32 influences mitochondrial function and cancer cell metabolism, we characterized the metabolome and transcriptome of INA-6 WT and KO cells from two different clones using mass spectrometry and next-generation RNA-sequencing, respectively." (PMID 35005550, 2022). "There is a constitutive level of intra-hepatic IL-32 expression in the non-cancer liver." (PMID 36438052, 2022). "Whether the effect of IL32 on cancer cells can lead to upregulation of these MHC molecules are yet to be demonstrated." (PMID 35563856, 2022). "As a pro-inflammatory cytokine, IL-32 was reported to be a poor prognostic factor in many cancers." (PMID 35428295, 2022). "It has been reported that IL-32 could promote the metastasis of cancer cells by up-regulation the expression of MMP2 and MMP9." (PMID 35428295, 2022). "Interleukin 32 (IL-32) is a novel cytokine related to cancer and immune diseases." (PMID 34414188, 2021). "Interleukin-32 (IL-32) is a novel cytokine regulating cancer development and inflammation." (PMID 35069212, 2021). "Indeed, various isoforms of IL-32 show differences in efficacy to elicit a specific effect and to induce different reactions in malignant tumors." (PMID 34682815, 2021). "Therefore, we compared gene expression for cancer-associated fibroblast (CAF) markers including MMP2, MMP9, MMP21, TGFA, CXCL12, ITGA3, FAPα, and IL32 in fibroblasts derived from normal skin and MF tumors." (PMID 33941102, 2021). "This observed discrepancy between IL-32 expression in cell lines versus whole tumors may be attributed to the source of IL-32 in human cancers." (PMID 32841222, 2020). "IL32 is a novel cytokine involved in inflammation and cancer development." (PMID 32308549, 2020). "The proinflammatory chemokine interleukin-32 is related to various diseases, including cancer." (PMID 33204366, 2020). "It has also been suggested that IL-32 may induce immunosuppression and allow cancer cells to evade immune system facilitating metastasis." (PMID 33020452, 2020). "IL-32 may modulate the VEGF expression during cancer, promoting the pro-angiogenic program, while in human bronchial epithelial cells, IL-32 appears to suppress the pro-angiogenic signals." (PMID 32487240, 2020). "Even though many researchers have demonstrated that IL-32 could activate NF-κB50,51], we previously found that IL-32 inactivates NF-κB in several cancer cells." (PMID 29467412, 2018). "Many studies have investigated IL-32 in various inflammatory disease as well as in cancer." (PMID 27589563, 2016). "The involvement of inflammatory cytokine IL-32 suggests a potential role in cancer development." (PMID 25909160, 2015). "Therefore, we expect that IL-32 regulation by ENO1 could be applied to treat cancers with inflammatory responses as well as inflammatory diseases." (PMID 38675491, 2024). "Thus, to determine if infections or cell death may induce cancer cell expression of IL-32 we here examined if IL-32 is induced by TLR agonists in MM cell lines and if expression of IL-32 correlates with TLR expression in primary MM cells." (PMID 36875074, 2023). "Consequently, it may either facilitate or hamper cancer development, gaining IL-32 a catching label of “frenemy in cancer”." (PMID 33020452, 2020). "In addition, IL-32 can enhance the cytotoxic effect of natural killer cells against cancer cells." (PMID 26241657, 2015). "It has been established that IL-32 may antagonize cancer growth." (PMID 25435980, 2015). "However, the role of IL32 in various cancers remains unclear." (PMID 38584169, 2024).
cancer (continued). "Our findings collectively suggest that YY1 transcriptionally upregulates IL32 secretion from pericytes, influencing their paracrine effect on TKI sensitivity in cancer cells." (PMID 39435643, 2024). "Furthermore, IL32 may be a potential prognostic and immune-related biomarker for cancer patients." (PMID 38584169, 2024). "YY1 was identified as a regulator of IL32 expression in PCs, and YY1 silencing countered the inhibitory effect of PCs on cancer cell TKI sensitivity." (PMID 39435643, 2024). "Mechanistically, YY1 transcriptionally up‐regulates IL32 secretion from PCs, which then activates the β5‐integrin‐Src‐Akt signaling pathway in EGFR‐mutant cancer cells to confer their TKI sensitivity." (PMID 39435643, 2024). "Overall, the findings highlight direct crosstalk between cancer cells and pericytes, impacting TKI sensitivity via IL32‐β5‐integrin paracrine signaling, proposing an enhanced therapeutic approach for EGFR‐mutated patients." (PMID 39435643, 2024). "We explored the correlation between IL32 expression and 150 immune regulatory factors (chemokines, MHC, immune inhibitors, immune stimulators) in cancer." (PMID 38584169, 2024). "Our data show that the use of proteasome inhibitors and DUB inhibitors affects IL-32 protein levels in T cells, which should be kept in mind when using DUB inhibitors in cancer treatments." (PMID 37313466, 2023). "Besides identifying IL-32 as a potential prognostic biomarker and treatment target in MM, our results provide insight into the metabolic functions of IL-32, which may be further exploited in other cancers and inflammatory diseases where IL-32 is known to play a central role." (PMID 35005550, 2022). "Our results demonstrate different roles of IL-32 in Treg cells and CD8+ T cells and suggest that it can potentially be a target for ESCC cancer immunosuppressive therapy." (PMID 34414188, 2021). "The θ isoform of IL-32 (IL-32θ) inhibits migration by hampering epithelial-mesenchymal transition (EMT) and temper the properties of cancer stem cells." (PMID 33020452, 2020). "Among cancers, CRC was accompanied by significantly lower IL-32 serum concentration than ESCC and GC." (PMID 33020452, 2020). "According to the presented data, it appears that decreased expression of IL-32 may inhibit production of proinflammatory and proangiogenic factor IL-17 and thus suppresses formation of new blood vessels which in turn results in diminished hematogenous metastatic potential of diffuse form of cancer." (PMID 30402092, 2018). "Recent study showed that IL-32 can affect the signaling of NF-κB and STAT3, which are confirmed to be the antiapoptotic and pro-angiogenic genes in cancer development." (PMID 25889282, 2015). "Compared to all other samples in the dataset, at least 7 of the 18 basal-like/TNBC samples expressed high levels of IL32; MCF10A and MCF12A (non-cancer) triple negative cell lines were included in the 11 samples that expressed low levels of IL32." (PMID 25100201, 2014). "While IL-32 has been shown to elicit various cellular responses and influence cancer and inflammatory processes, the specific receptor that directly binds and interacts with IL-32 has not yet been definitively identified." (PMID 38272918, 2024). "Interestingly, in PT2 the transcriptional signature was one of inflammation and regeneration gene expression (SOX9, IL32, and VCAM1), which has been related to carcinogenesis and cancer progression." (PMID 36180422, 2022). "Interleukin-32 (IL-32) is a nonclassical cytokine expressed in cancers, inflammatory diseases, and infections." (PMID 35005550, 2022). "IL-32 is more highly expressed in immune cells than in nonimmune cells and is closely related to anticancer effects in various types of cancer." (PMID 34682815, 2021). "Despite growing interest in IL-32, there is a scarcity of data concerning its status in the GIT cancers while its diagnostic utility has not been previously determined." (PMID 33020452, 2020).